TLR4 (toll like receptor 4)
Diseases named in the same sentence as TLR4 in open-access papers (continued):
Sharing a sentence is not in itself a finding about the gene and the disease.
gastric ulcer (7 papers, 2013 to 2025). An ulcerated lesion in the mucosal surface of the stomach. "By contrast, pre-treatment of gastric ulcers mice with DPHs decreased the expression of proteins associated with the TLR4/MYD88/NF-κB signaling pathway, decreased the activities of inflammation-related enzymes, iNOS, and COX-2, and the production and release of inflammatory factors." (PMID 34249268, 2021). "The main purpose of the current investigation was to evaluate the in vivo anti-inflammatory and anti-ulcerogenic capabilities of BIEE against ethanol-induced gastric ulcers in rats via the HMGB1/TLR-4/NF-B signaling pathway." (PMID 37371993, 2023). "In summary, these results provided the evidence that SAFP exerted a beneficial effect on a WIRS-induced gastric ulcer via blocking the TLR4 signaling pathway and activating the Nrf2 signaling pathway." (PMID 35681318, 2022). "Acupuncture at back-shu and front-mu acupoints played a role in preventing gastric ulcer by inhibiting extracellular signals, stimulating kinases in serum and gastric tissues, and activating the inhibition of the TLR4 signaling pathway." (PMID 33628315, 2021). "TLR4 and RAGE deficiency promoted gastric ulcer formation and prevented the increase in TNFα mRNA expression after ulceration, whereas TLR2 deficiency affected neither the ulcer index nor the expression of TNFα mRNA." (PMID 24244627, 2013). "Downregulation of TLR4 plays a vital role in gastric ulcer healing." (PMID 37371993, 2023). "Thus, it is plausible that the pathogenesis of stress-induced gastric ulcer involves the TLR4/MyD88/NF-κB signal transduction pathway." (PMID 33628315, 2021). "Thus, we showed that HMGB1 is a complicating factor in the gastric ulcer healing process, which acts through TLR4 and RAGE to induce excessive inflammatory responses." (PMID 24244627, 2013). "The compound has proved its potency as an antiulcer agent towards Ethanol-induced gastric ulcer and the mechanism was possibly elucidated via Nrf2/HO1 and HMGB1/TLR4/NF-κB pathways, along with identification of the relation between them." (PMID 37371993, 2023). "Quercetin could enhance gastric ulcer treatment through the Nrf2/HO-1 and HMGB1/TLR4/NF-κB pathways, protecting gastric lesions from ethanol." (PMID 40017602, 2025). "Our results clearly showed that TLR4 and RAGE play crucial roles in gastric ulcer healing." (PMID 24244627, 2013).
immunotoxicity (7 papers, 2019 to 2025). "Taken together, BB-80 and OH-BB-80 mediate immunotoxicity and early developmental suppression associated with the TLR4/NF-κB signaling pathway." (PMID 40278609, 2025). "The roles of TLR2 and TLR4, as well as the NF-κB pathway, in mediating immunotoxicity to PBBs and their transformations need to be further investigated." (PMID 40278609, 2025). "Previous studies have shown that OTA mediated immunotoxicity of the TLR4/MyD88 signaling pathway by inducing an increase in reactive oxygen species in porcine alveolar macrophages." (PMID 31533259, 2019). "These immunotoxicity and inflammatory responses triggered by AFB1 exposure involve multiple signaling pathways, including the cell cycle arrest, MAPK, NF-κB, Toll-like receptor 4 (TLR4), PKC, Wnt/β-catenin, and NLRP3 pathways." (PMID 39765856, 2024). "Significant increases in immune-related protein indicators (NF-κB, TNF-α, IL-1β and TLR4) were detected in our study, indicating that 6:2 FTSA amplifies the inflammatory damage profile and induces organismal immunotoxicity in zebrafish larvae." (PMID 37235273, 2023). "Previous studies have shown that the inflammatory response and immunotoxicity induced by ZEA may involve multiple pathways, such as NF-kB, Toll-like receptor 4 (TLR4), NRLP3, and MAPK pathways." (PMID 39456789, 2024).
intracranial hemorrhage (7 papers, 2019 to 2023). Bleeding within the SKULL, including hemorrhages in the brain and the three membranes of MENINGES. "TLR4, TNF and NLR deficiency significantly attenuated ischemic brain injury, brain hemorrhage and hemorrhagic transformation to some extent by decreasing the inflammatory response in the brain." (PMID 36755018, 2023). "It was found that neutrophils express TLR2 and Toll-like receptor 4 (TLR4), and brain hemorrhage is not only dependent on TLR2 receptors but also requires TLR4 receptors." (PMID 37168122, 2023). "The CP thus appears to respond in a TLR4-dependent manner to intracranial hemorrhage with epithelial upregulation of adhesion molecules, release of centrally and peripherally oriented chemoattractants, and CSF hypersecretion." (PMID 36482445, 2022). "For example, in intracranial hemorrhage, free heme induces microglial activation via TLR4 and the MyD88/TRIF signaling pathway, resulting in the increased expression of TNF." (PMID 31358003, 2019). "It was found that the levels of IL-1β, IL-6, and TNF were significantly lower in TLR2 and TLR4 knockout mice after brain hemorrhage than in wild-type mice, thus supporting the link between TLR2 and TLR4 activation and M1 microglia." (PMID 36296682, 2022). "In addition, TLR2-TLR4 heterodimers trigger inflammatory responses, suggesting a role for TLR2 in brain hemorrhage similar to that of TLR4." (PMID 36296682, 2022).
left ventricular hypertrophy (7 papers, 2014 to 2022). Enlargement of the LEFT VENTRICLE of the heart. "The first demonstration came from a TLR4 knockout mice model, which develops less-severe left ventricular hypertrophy following aortic banding compared to its respective sham controls." (PMID 27347925, 2016). "All of these markers were normalized after anti-TLR4 antibody treatment, but neither blood pressure nor left ventricular hypertrophy was modulated, indicating that inflammation through TLR4 signaling contributed only to pro-fibrotic phenotype." (PMID 27347925, 2016). "The decrease of the inflammatory response upon TLR2 and -9 ligand challenge in TAC Tlr4-/- mice demonstrates that a lack of TLR4 signaling does not only prevent left ventricular hypertrophy but also protects the mice from a cardiac stress induced hyperinflammatory reaction." (PMID 26588247, 2015).
limb ischemia (7 papers, 2012 to 2025). A ischemia that involves the limb. "Tetrahydrocurcumin (THP) induces the polarization of M1 macrophages to M2 by inhibiting the TLR4/NF-κB/NLRP3 signaling pathway, thereby alleviating acute lung injury caused by limb ischemia-reperfusion in rats." (PMID 40538538, 2025). "It was shown that IPC ameliorated AKI induced by limb ischemia/reperfusion via inhibiting TLR4 and NF-κB signaling in rats." (PMID 35224648, 2022). "In summary, our data suggest that mediators of innate immunity, including TLR2 and TLR4, play important roles in muscle regeneration and angiogenesis in the setting of limb ischemia." (PMID 23209800, 2012).
mycoplasma pneumonia (7 papers, 2017 to 2025). "Mechanistically, CD16+ monocytes have been shown to mediate pulmonary inflammation through TLR4‐dependent IL‐23 secretion in Mycoplasma pneumonia, findings that are consistent with our current results." (PMID 40936181, 2025). "This miRNA affects pulmonary inflammatory factors and cell apoptosis in mice with mycoplasma pneumonia by regulating the TLR4/MyD88/NF-κB signaling pathway." (PMID 39328420, 2024). "Upregulation of miR-143-3p expression reduced TNFα, MyD88, p50, and alveolar epithelial cell apoptosis in mycoplasma pneumonia mice by inhibiting TLR4/MyD88/NF-κB axis." (PMID 35812870, 2022). "The TLR4 gene was described as one of the important immunological factors influencing for example the development of mycoplasma pneumonia of swine." (PMID 29273011, 2017). "mRNA and protein expressions of apoptosis-related factors Bax and Bcl-2 were measured by qRT-PCR and Western blot in order to investigate how miR-143-3p mediated TLR4/MyD88/NF-κB signaling pathway to work on the apoptosis of alveolar epithelial cells of mice with mycoplasmal pneumonia." (PMID 32597476, 2020). "We speculated that there might be some miRNAs that could regulate inflammatory cytokine release and alveolar epithelial cell apoptosis in mycoplasmal pneumonia by affecting TLR4/MyD88/NF-κB signaling pathway." (PMID 32597476, 2020). "Therefore, our study was aimed at exploring whether miR-143-3p could affect inflammatory factors’ levels and alveolar epithelial cell apoptosis in mice with mycoplasmal pneumonia by regulating TLR4/MyD88/NF-κB signaling pathway." (PMID 32597476, 2020). "Therefore, up-regulation of miR-143-3p expression may ameliorate pulmonary inflammatory factors levels and reduce alveolar epithelial cell apoptosis in mycoplasmal pneumonia mice by inhibiting TLR4/MyD88/NF-κB signaling pathway." (PMID 32597476, 2020). "During infection with Mycoplasma pneumonia, Staphylococcus aureus, and Pasteurella multicoda DDX5 is degraded, preventing decay of Tlr2 and Tlr4 transcripts and promoting upregulated protein levels of TLR2 and TLR4 critical for induction of antibacterial responses." (PMID 39620586, 2025).
Neonatal sepsis (7 papers, 2020 to 2026). Systemic inflammatory response to infection in newborn babies. "The single-nucleotide polymorphisms (SNPs) in TLR4 were regarded as genetic modulators of infection in neonatal sepsis." (PMID 32908583, 2020). "(i) It is an innovative study that directs the spotlight onto the effect of the presence of TLR2, TLR4, IL6, and IL10 polymorphisms in the context of early neonatal sepsis in preterm neonates." (PMID 41598258, 2026). "TLR4 had been reported to be a key regulator in neonatal sepsis." (PMID 32908583, 2020).
overnutrition (7 papers, 2012 to 2023). An imbalanced nutritional status resulting from excessive intake of nutrients. "Furthermore, brain-specific inhibition of TLR4 signaling reproduced the protective effects of whole-body TLR4 deficiency against overnutrition." (PMID 22328600, 2012). "In addition to directly activating proinflammatory kinase pathways upon overnutrition, TLR4 activation has been shown to induce intracellular ER stress to indirectly cause metabolic inflammation in the hypothalamus." (PMID 22328600, 2012). "Overnutrition, especially in the form of HFD feeding, was shown to activate TLR4 signaling and downstream IKKβ/NF-κB pathway, leading to metabolic derangements such as central leptin resistance, systemic glucose intolerance, and weight gain." (PMID 22328600, 2012).
pneumococcal meningitis (7 papers, 2014 to 2024). An acute purulent infection of the meninges and subarachnoid space caused by Streptococcus pneumoniae, most prevalent in children and adults over the age of 60. "Using an established mouse model, the present study demonstrates a partial role for a TLR2- and TLR4-mediated acute inflammatory response in modulating the long-term neurological outcomes seen in mice that have survived pneumococcal meningitis due to CEFT treatment." (PMID 31700009, 2019). "Thus, it appears possible that expression of CCL20 is mediated by TLR2 and TLR4 activation during pneumococcal meningitis." (PMID 24699535, 2014). "We conclude that TLR2 and TLR4 are central to regulating the host inflammatory response in pneumococcal meningitis, which may mediate diverse compensatory mechanisms that protect the host not only against mortality but also long-term neurological complications." (PMID 31700009, 2019). "In pneumococcal meningitis, the interaction of TLR2 and TLR4 is required for the immunologic reaction." (PMID 31791382, 2019). "Here we investigated both the acute immunological reaction and the long-term neurobehavioural consequences of experimental pneumococcal meningitis in mice lacking both TLR2 and TLR4." (PMID 31700009, 2019).
status epilepticus (7 papers, 2020 to 2025). Status epilepticus is defined as a continuous seizure lasting more than 30 min, or two or more seizures without full recovery of consciousness between any of them. "HSP70 serves as another modulator of TLR4-associated signaling, which proved to be up-regulated in a post-status epilepticus model in rats." (PMID 31959173, 2020). "Thereby the increase in patients with seizure clusters was rather related to an upregulation of expression rates per cell, whereas the increase in patients with status epilepticus seems to be associated with an expansion of the population of cells expressing TLR4 above control level." (PMID 31959173, 2020). "Based on mouse models of status epilepticus (SE) induced by pilocarpine, and treated with 15 mg/kg (+)-borneol, western-blot was used to detect the expressions of NeuN, Iba-1, TLR4, p65 and p-p65 in the hippocampus." (PMID 39605791, 2024). "A good example is celecoxib, blocking the cyclooxygenase 2 and HMGB1/TLR-4 pathways, which was evaluated in rats surviving lithium-pilocarpine status epilepticus." (PMID 34575901, 2021). "The anti-inflammatory drug celecoxib (an inhibitor of the cyclooxygenase 2 and HMGB1/TLR-4 pathways) has been documented to significantly reduce the remote consequences of status epilepticus in rats." (PMID 34575901, 2021). "Analysis of TLR4 expression revealed an induction in the hippocampal CA3 region in both subgroups, i.e. dogs with recent seizure clusters and status epilepticus." (PMID 31959173, 2020).
synovitis (7 papers, 2016 to 2025). Inflammation of a synovial membrane. "A plausible explanation for this observation is the potential role of TLR2 and TLR4 signaling in the pathogenesis of synovitis." (PMID 41282165, 2025). "Synovial TLR4 was observed to be higher in RA patients and found to positively correlate with synovitis." (PMID 37063906, 2023). "Additionally, obese patients have a higher incidence and severity of synovitis, characterized by synovial fibrosis, increased macrophage infiltration, and elevated Toll-like receptor-4 (TLR4) expression." (PMID 40917583, 2025). "Once OA synovitis starts, IL-1, TNF-α and IL-6 are over-produced and secreted to synovial fluid through activation of TLR4 by synovial cells." (PMID 36241903, 2022). "Concerning that TLR4 can initiate immune reactions during the process of long‐term burden, it is reasonable to explore the effect of TLR4 in TMJOA, which has been characterized by synovitis, condylar degeneration and osteophyte." (PMID 32914937, 2020). "Indeed, recent studies reported that TLR4 elevated in the synovial membrane of temporomandibular joint (TMJ) synovitis induced by occlusal interference, and inhibition of TLR4 by TMJ injection of TAK‐242 could alleviate the level of synovitis, suggesting TLR4 participates in TMJ synovitis." (PMID 32914937, 2020).
temporal lobe epilepsy (7 papers, 2022 to 2025). A localization-related (focal) form of epilepsy characterized by recurrent seizures that arise from foci within the temporal lobe, most commonly from its mesial aspect. "Of note, an elevated expression of TLR4 was identified in surgical specimens of drug-resistant temporal lobe epilepsy, focal cortical dysplasia, and tuberous sclerosis patients." (PMID 35647304, 2022). "In a rat model of temporal lobe epilepsy, it has been shown that HMGB1/TLR4 is overexpressed and may induce inflammatory responses and reorganization of neuronal synaptic transmission through the p38MAPK signalling pathway." (PMID 39046369, 2024). "Parallel to our findings, HMGB1 release from neurons was reported to activate TLR4 in astrocytes but not microglia in mouse models of seizures, as well as specimens from patients with temporal lobe epilepsy with hippocampal sclerosis." (PMID 38082296, 2023).
triple-negative breast carcinoma (7 papers, 2014 to 2025). An invasive breast carcinoma which is negative for expression of estrogen receptor (ER), progesterone receptor (PR), and human epidermal growth factor receptor 2 (HER2). "In summary we have demonstrated that elevated expression of fetuin-A in a triple negative breast cancer cell line promotes invasion capacity of the cells and upregulates TLR4 expression in these cells." (PMID 40124677, 2025). "Our previous study proved that ΔA146Ply inhibited autophagy in triple-negative breast cancer cells by activating TLR4 and MR." (PMID 35538212, 2022). "In a previous study, we showed that ΔA146Ply, a mutant of pneumolysin that lacks hemolytic activity, inhibited autophagy of triple-negative breast cancer cells by activating mannose receptor (MR) and toll-like receptor 4 (TLR4) and that tumor-bearing mice tolerated ΔA146Ply well." (PMID 35538212, 2022). "ΔA146Ply, a mutant of pneumolysin (Ply) that lacks hemolytic activity, has been shown to inhibit autophagy in triple-negative breast cancer cells by activating toll-like receptor 4 (TLR4) and mannose receptor (MR), which suggests that ΔA146Ply may act on other cells that express TLR4 and MR." (PMID 35538212, 2022). "A recent study suggested that LPS/TLR4-induced signaling cascades leads to inducible nitric oxide synthase (iNOS) induction, and inhibition of iNOS might be as a novel effective target therapy against triple-negative breast cancer." (PMID 28950845, 2017). "The basal like triple negative breast cancer cell line, MDA-MB-468 typically express very low levels of TLR4." (PMID 40124677, 2025). "In triple-negative breast cancer cells, PTX3 inhibition led to less aggressive tumor behavior through the TLR4 signaling pathway." (PMID 39594709, 2024). "In conclusion, PsA-D induced cytokine blockade and p65 phosphorylation in triple negative breast cancer cells does not dependent on TLR4." (PMID 28832545, 2017).
Acanthamoeba infection (6 papers, 2014 to 2023). "Increased TLR4 gene expression in hosts with normal immunity infected with Acanthamoeba suggests the involvement of the studied receptor in the course of acanthamoebiasis." (PMID 37242301, 2023). "The first evaluated the effects of Artemisia annua extracts on the expression of TLR2 and TLR4 in the brains of mice with Acanthamoeba infection." (PMID 32679734, 2020). "The second study evaluated the effects of Artemisia annua extracts on TLR2 and TLR4 expression in the lungs of mice with acanthamoebiasis." (PMID 32679734, 2020). "The important thing for our studies was the expression of TLR4 in the immunocompetent host (significantly higher at eight days post Acanthamoeba infection) and immunoexpression of TLR4 in the skin (the area of connective tissue of the dermis) were observed on the same day." (PMID 37242301, 2023). "The course of disseminated acanthamoebiasis may be influenced by the host's immunological status, and the observed changes in expression of TLR2 and TLR4 in the host's organs may indicate the role of these receptors in the pathomechanism of acanthamoebiasis." (PMID 31309100, 2019). "The present study is the first to compare the in vitro and in vivo activation of TLR4 simultaneously in response to pathogenic and non-pathogenic Acanthamoeba infection." (PMID 24633052, 2014). "Additionally, TLR4 is the receptor that stimulates the pathways of TLR4-MyD88-NF-κB and TLR4-ERK1/2 and activates inflammatory cytokines in acanthamoebiasis." (PMID 37242301, 2023).
acute chest syndrome (6 papers, 2018 to 2024). A vaso-occlusive crisis of the pulmonary vasculature occurring in patients with sickle cell disease. "Free heme released by hemolyzed red blood cells can bind to myeloid differentiation factor-2 (MD-2) and activate TLR4 pro-inflammatory signaling on endothelium to promote vaso-occlusion and acute chest syndrome in murine models of SCD." (PMID 33841413, 2021). "Heme and hemoglobin also represent erythrocytic danger-associated molecular pattern molecules (eDAMPs), which may activate endothelial inflammation through TLR-4 signaling and promote the development of complications, such as acute chest syndrome." (PMID 32231672, 2020). "However, TLR4 inhibition (by the use of TAK-242) and hemopexin replacement therapy, prior to hemin infusion, protected sickle mice from developing acute chest syndrome." (PMID 32231672, 2020).